CEL (carboxyl ester lipase)
Diseases named in the same sentence as CEL in open-access papers:
CEL is named in the same sentence as 66 diseases in open-access papers, as found by Europe PMC text mining. Sharing a sentence is not in itself a finding about the gene and the disease. The quoted sentences say what the papers report.
diabetes (27 papers, 2011 to 2026). "MODY caused by mutations in the CEL gene (MODY8) ischaracterized by dominantly inherited diabetes mellitus manifestingin early adulthood." (PMID 40840513, 2025). "The CEL A689P missense mutation will expand the knowngenotype–phenotype correlation in diabetes if it can be demonstratedthat the variant is pathogenic." (PMID 40840513, 2025). "MODY8 is causedby mutations in CEL and is a genetic disorder characterized bypancreatic exocrine dysfunction with childhood onset and diabetes starting inadulthood." (PMID 40840513, 2025). "MODY8 is also considered to be a protein-misfolding diseasebecause a heterozygous single nucleotide deletion causes the production ofmutant CEL protein leading to diabetes and exocrine dysfunction." (PMID 40840513, 2025). "For example, variants in carboxyl ester lipase gene VNTR have been associated with diabetes and exocrine pancreatic dysfunction." (PMID 38707821, 2024). "Mutations in carboxyl ester lipase (CEL) has been shown to cause a syndrome of diabetes and pancreatic exocrine dysfunction." (PMID 38027148, 2023). "Mutations in the CEL gene result in exocrine pancreatic insufficiency and eventual progression to diabetes." (PMID 35769082, 2022). "Maturity Onset Diabetes of the Young type 8 (MODY8) is a form of diabetes that results from mutations in Carboxyl Ester Lipase (CEL)." (PMID 35769082, 2022). "Previous studies have reported that CEL mutations can lead to childhood-onset pancreatic exocrine dysfunction and diabetes mellitus from adulthood." (PMID 33661921, 2021). "On the other hand, a single base insertion (1686delT; C563fsx673) causes polygenic diabetes resulted by truncation of the CEL, thus suggesting a frame shift deletion mutation in variable number tandom repeats (VNTR) in the 11th exon of CEL gene." (PMID 29867778, 2018). "We have created an over-expressing transgenic mouse model, TgCEL, to study CEL-MODY, a human monogenic syndrome of diabetes and pancreatic exocrine dysfunction caused by mutations in the gene encoding carboxyl-ester lipase." (PMID 23565203, 2013). "CEL-MODY is a monogenic form of diabetes with exocrine pancreatic insufficiency caused by mutations in CARBOXYL-ESTER LIPASE (CEL)." (PMID 23565203, 2013). "Human CEL mutation carriers develop evidence of pancreatic exocrine disease preceding diabetes and pancreatic lipomatosis." (PMID 23565203, 2013). "In humans, frameshift mutations in CEL cause maturity-onset diabetes of the young type 8 (MODY8), a monogenic syndrome of diabetes and pancreatic exocrine dysfunction." (PMID 30305605, 2018). "The first report described variants in the gene encoding carboxyl ester lipase (CEL) that result in a form of autosomal dominant CP characterized by early-onset pancreatic insufficiency and diabetes." (PMID 30408063, 2018). "The number of variants detected was greater than in Stage 1 since five additional monogenic diabetes genes (CEL, EIF2AK3, ABCC8, BLK, and KLF11) were sequenced." (PMID 29207974, 2017). "We excluded the remaining MODY genes (CEL, PDX1, PAX4, BLK, KLF11, NEUROD1) from this analysis since either very few missense mutations in these genes have been associated with early onset diabetes or the genetic evidence for association is limited." (PMID 29207974, 2017). "In summary, we identified variants in BLK, CEL, KLF11, PDX1, and PAX4 that may contribute to various forms of diabetes, including rare MODY subtypes." (PMID 41153735, 2025). "Only one of the four mutation carriers was from the sub-group with early onset diabetes, indicating that, unlike classical MODY genes, heterozygous protein truncating mutations that affect the CEL gene are unlikely to be a strong risk factor for early onset diabetes." (PMID 29207974, 2017).
diabetes (continued). "Moreover, rare CEL gene defects in this region are responsible for a monogenically derived diabetes condition called maturity-onset diabetes of the young type 8 (MODY8), also known as diabetes and pancreatic exocrine dysfunction (DPED), which causes a defect in insulin secretion." (PMID 22162806, 2011). "After adjustment for age, sex and diabetes status, protein-bound CML was positively correlated with sVCAM-1; free CEL with sVCAM-1 and sThrombomodulin; glyoxal with sThrombomodulin; and methylglyoxal with sVCAM-1 (correlation coefficients ranged from 0.36 to 0.44)." (PMID 31408493, 2019). "In addition, the associations of protein-bound CEL with C3a, and of protein-bound CML and CEL with sC5b-9, were different in individuals with and without diabetes." (PMID 31993713, 2020).
MODY (16 papers, 2012 to 2025). "Additionally, pathogenic genetic mutations in CEL/BSDL have been demonstrated in individuals with maturity-onset diabetes of the young type 8 (MODY8), neonatal-onset T1D, and atypical T2D." (PMID 38390030, 2023). "For the CEL, PDX1, INS, KCNJ11 and ABCC8 genes, MODY is caused only by specific variants resulting in dominant‐negative/gain of function effects; null variants in these genes do not cause MODY." (PMID 35445424, 2022). "To date, 14 disease genes for MODY are identified; most of them are transcription factors MODY1 (HNF4A), MODY3 (HNF1A), MODY4 (PDX1), MODY5 (HNF1B), MODY6 (NEUROD1/BETA2), MODY7 (KLF11), MODY8 (CEL), MODY9 (PAX4), MODY11 (BLK), and MODY14 (APPL1)." (PMID 31145732, 2019).
chronic pancreatitis (9 papers, 2015 to 2025). A chronic inflammatory process causing damage and fibrosis of the pancreatic parenchyma. "As previously observed in PAC, MODY-8 diabetes, and chronic pancreatitis, aberrant variants of BSDL (BSDL-InsC, CEL-MUT, CEL-HYB) with impaired secretion should either be degraded or presented at the cell surface as aggregates and further degraded after recapture." (PMID 29552330, 2018). "Another report shows that a recombined allele of CEL and its pseudogene CELP confers susceptibility to chronic pancreatitis." (PMID 30305605, 2018). "CEL-HYB was present in 0.7% of the control cohorts and in 3.7% of the case group cohort, underlining a substantial chronic pancreatitis risk associated with the recombined allele (odds ratio = 5.2)." (PMID 29552330, 2018). "CEL-HYB is a hybrid allele that arose from a crossover between the 3’ end of the Carboxyl ester lipase (CEL) gene and the nearby CEL pseudogene (CELP) and was recently identified as a risk factor for chronic pancreatitis." (PMID 28881607, 2017). "Missense mutations in pancreatic secretory enzymes such as CPA1, PRSS1, CEL and PNLIP may lead to protein misfolding and the development of ER stress, which may predispose to chronic pancreatitis." (PMID 35704637, 2022). "Since the clinical syndrome of chronic pancreatitis is uncommon, it is likely that most CEL-HYB carriers do not develop pancreatitis." (PMID 28881607, 2017). "Additionally, non-allelic homozygous recombination of CEL and its neighboring pseudogene CELP results in a hybrid protein CEL-HYB1 characterized by impaired activity, secretion defect, misfolding, and increased susceptibility for chronic pancreatitis." (PMID 35704637, 2022).
Obesity (9 papers, 2020 to 2025). Accumulation of substantial excess body fat. "In consistence with our results, it was observed that high fat diet (HFD) supplementation decreased mRNA level of CEL, and its knockout led to the protection of diet-induced obesity." (PMID 32899471, 2020). "DEGs included a wide range of obesity marker genes, including obesity and lipid metabolism genes, such as acyl-CoA thioesterase, carboxyl ester lipase, and apolipoprotein C3." (PMID 32899471, 2020).
pancreatitis (8 papers, 2007 to 2025). Inflammation of the pancreas. "Germline testing, currently for recommended etiologic mutations associated with pancreatitis, includes evaluation for pathogenic variants in the CEL, CFTR, CPA1, CTRC, PRSS1, and SPINK1 genes in symptomatic individuals." (PMID 33375361, 2020). "It has been shown that the CEL gene and is one of the risk factors for pancreatitis and that pancreatitis patients have a high probability of developing pancreatic cancer, while a direct relationship between the CEL gene and pancreatic cancer cannot be completely ruled out." (PMID 38074669, 2023). "Most recently, a Japanese study has reported a promising association between the risk of developing pancreatitis and a polymorphism of the gene for one of the candidate FAEE synthase enzymes (i.e., carboxyl ester lipase [CEL]) and the risk of developing alcoholic pancreatitis." (PMID 17718401, 2007). "Genetic analyses suggested that heterozygous CEL misfolding mutations may predispose to the disease, but do not impel pancreatitis per se." (PMID 35704637, 2022). "Other genetic factors related to pancreatitis are Calcium Sensing Receptor (CASR), Claudin 2 (CLDN2), Carboxyl Ester Lipase (CEL), Cathepsin B (CTSB), Myosin IXB (MYO9B), Ubiquitin Protein Ligase E3 Component N-Recognin 1 (UBR1), and Fucosyltransferase 2 (FUT2)." (PMID 36434531, 2022). "CEL-HYB carriers were not more likely to report a history of pancreatitis." (PMID 28881607, 2017).
pancreatic cancer (6 papers, 2019 to 2024). "Trypsin, chymotrypsin, lipase, amylase, and carboxyl ester lipase are some of the exocrine pancreatic enzymes used to differentiate ACC from other pancreatic tumors." (PMID 39410042, 2024). "The tissue stemmed from patients diagnosed with pancreatic cancer, but CEL mRNA is absent also from normal human pancreatic ductal cells." (PMID 31963687, 2020).
pancreatic insufficiency (6 papers, 2011 to 2025). "SPINK1-related SIIEPI also warrants comparison with other genetic forms of early-onset exocrine pancreatic insufficiency, particularly those caused by pathogenic or predisposing variants in CFTR and CEL." (PMID 41009946, 2025). "Heterozygous single-nucleotide deletions in CEL cause pancreatic insufficiency and the monogenic diabetes syndrome MODY8, whereas CEL-HYB1, a hybrid gene between CEL and its neighboring pseudogene increases risk for idiopathic chronic pancreatitis." (PMID 35428786, 2022). "CEL, CPA1, and CPB1 code for carboxyl ester lipase, carboxypeptidase A1, and carboxypeptidase B1, respectively, and their downregulation is again indicative of pancreatic exocrine insufficiency associated with onset of malignancy in benign IPMNs." (PMID 34790815, 2021).
breast carcinoma (5 papers, 2020 to 2024). "For CEL (Carboxyl ester lipase), it was reported that it is highly expressed in breast cancer tissues and is associated with poor overall survival and clinical pathological characteristics." (PMID 38279987, 2024).
pancreatic disease (3 papers, 2020 to 2022). "Taken together, our findings provide valuable insight into how the pathogenic CEL variants predispose to pancreatic disease and why these disorders develop slowly over time." (PMID 31963687, 2020). "Mutations in the gene encoding the digestive enzyme carboxyl ester lipase (CEL) are linked to pancreatic disease." (PMID 31963687, 2020).
type 1 diabetes (3 papers, 2017 to 2025). "As it has been reported, these compounds are present in the plasma of diabetic patients in a concentration up to 1.2 μmol/L for CEL and 2.9 μmol/L for CML and at a concentration up to 1.7 μmol/L and 4.9 μmol/L, respectively, in the plasma in type I diabetes and impaired renal function patients." (PMID 34422213, 2021).
acute pancreatitis (2 papers, 2014 to 2024). An acute inflammatory process that leads to necrosis of the pancreatic parenchyma. "Non-oxidative metabolism of ethanol (NOME) produces fatty acid ethyl esters (FAEEs) via carboxylester lipase (CEL) and other enzyme action implicated in mitochondrial injury and acute pancreatitis (AP)." (PMID 24162590, 2014).
alcoholic liver cirrhosis (2 papers, 2016 to 2024). A disorder of the liver characterized by the presence of fibrotic scar tissue instead of healthy liver tissue. "Carboxyl ester lipase is implicated in reverse cholesterol transport and confers susceptibility to alcoholic liver cirrhosis." (PMID 39684755, 2024).
alcoholic pancreatitis (2 papers, 2007 to 2016). Acute or chronic inflammation of the pancreas due to excessive alcohol drinking. "Carboxyl-ester lipase (CEL) contributes to fatty acid ethyl ester metabolism, which is implicated in alcoholic pancreatitis." (PMID 27802312, 2016).
Anxiety (2 papers, 2017 to 2020). Intense feelings of nervousness, tension, or panic often arise in response to interpersonal stresses. "Meanwhile, other CeL circuits have been shown to underlie the switch between innate and conditioned fear, and anxiety generalization." (PMID 28374004, 2017). "The BSTDL and CeL have been shown to be involved in fear and anxiety." (PMID 33344719, 2020).
colorectal cancer (2 papers, 2016 to 2024). A primary or metastatic malignant neoplasm that affects the colon or rectum. "In particular, we found that the carboxyl ester lipase (CEL) gene product was significantly upregulated across all colorectal cancer stages, as well as at significantly higher transcriptional levels both before and after lymph node metastasis." (PMID 39139583, 2024).
co-infection (1 paper, 2022). "The enzyme data was further supported by the expression of R. solani PNL, PG, and CEL genes that were highly induced at early stages of root infection by R. solani alone or during co-infection with L. mesenteroides." (PMID 35163289, 2022).
Constipation (1 paper, 2024). Infrequent or difficult evacuation of feces. "The present results suggest that C3 deficiency-induced constipation may be associated with 1237 upregulated genes including PNLIP, CEL, CPB1, CTRL, PNLIPRP1, and REG1 as well as 1292 downregulated genes including Eif2s3y, UTY, KDM5D, IGKV6-32, Olfr870, and DDX3Y." (PMID 39273477, 2024).
cyst (1 paper, 2021). A sac-like closed membranous structure that may be empty or contain fluid or amorphous material. "Such comparison resulted in 4 upregulated (CP, CEACAM5, DMBT1, and KRT6A) and 8 downregulated (CEL, CPA1, CPB1, ALB, SERPINA4, CA2, CLU, and AMBP) DEGs secreted in cyst fluid of high-risk IPMNs." (PMID 34790815, 2021).
diabetic ketoacidosis (1 paper, 2025). The metabolic condition resulted from uncontrolled diabetes mellitus, in which the shift of acid-base status of the body toward the acid side because of loss of base or retention of acids other than carbonic acid is accompanied by the accumulation of ketone bodies in body tissues and fluids. "A Japanese case report described a CEL mutation in exon 2 (c.146_147delCT; p.Ser49CysfsTer52) in a 13-year-old girl presenting with her first episode of diabetic ketoacidosis (DKA) and impaired insulin secretion." (PMID 41153735, 2025).
E. coli infection (1 paper, 2024). "Protein network analysis indicated that genes such as FOS, CTLA4, APOA1, CEL, FRK, and AGTR1 had the strongest association with other genes, highlighting their crucial roles in E. coli infection." (PMID 39707535, 2024).
endometriosis (1 paper, 2025). The growth of functional endometrial tissue in anatomic sites outside the uterine body. "The CEL gene has not yet been studied in the context of endometriosis." (PMID 40698088, 2025). "BIRC3, CEL, and LEFTY1 were significantly less expressed in the endometrium of women with endometriosis than without (logFC = −0.79, p = 0.0051; logFC = −0.52, p = 0.0051; logFC = −0.61, p = 0.0099, respectively)." (PMID 40698088, 2025).
glioblastoma (1 paper, 2017). The most malignant astrocytic tumor (WHO grade IV). "For instance, PCSK9 (6.3-fold increase), CEL (15.1-fold increase), or GSTM5 (3.9-fold decrease), despite their relatively important deregulation, had only been reported in lung cancer for PCSK9, pancreatic and nasopharyngeal carcinoma for CEL, Barret esophagus and glioblastoma for GSTM5." (PMID 28962550, 2017).
hepatocellular carcinoma (1 paper, 2022). A malignant tumor that arises from hepatocytes. "A study with mice with hepatocellular carcinoma was able to identify that the oncogenes Carboxyl ester lipase (Cel) gene and Harvey rat sarcoma virus oncogene 1 (Hras) had a higher frequency of mutations in obese mice when compared to lean mice." (PMID 36262532, 2022).
infection (12 papers, 2011 to 2025). The state of being infected such as from the introduction of a foreign agent such as serum, vaccine, antigenic substance or organism. "Infection reduced relative abundance of bacterial taxa and some predicted metabolic pathways known for short-chain fatty acid production in CeL, CeM, and IlL microbiota, but further understanding of metabolic function is required." (PMID 38729976, 2024).
cancer (7 papers, 2019 to 2023). A tumor composed of atypical neoplastic, often pleomorphic cells that invade other tissues. "We found that the expression levels of 1624 ceMs occurring in 32 cancer types were significantly different between the corresponding mutant and control samples and were regulated by 2849 ceL." (PMID 34079798, 2021). "The differentiated cancer cells had significantly increased the levels of CA2 (a ductal epithelial cell marker), while the levels of CEL (an acinar cell marker) did not change." (PMID 35673567, 2022).
tumor (7 papers, 2020 to 2025). "The comparisons between tumor tissue and normal tissue showed that PDE6G and CYP3A4 expression, but not CEL expression, in PCa tissue was considerably higher than that in normal prostate tissue." (PMID 38297388, 2024).
CEL also shares sentences with these, for which no sentence is quoted: hyperlipidemia (11 papers); diabetes type 2 (5); Hypercholesterolemia (4); HIV-1 infection (3); AIDS (2); Arthritis (2); viral infection (2); atherosclerosis (1); CF liver disease (1); cholesterol metabolism disorder (1); colon adenocarcinoma (1); COVID-19 (1); dyslipidemia (1); eosinophilia (1); eosinophilic disorders (1); glucose metabolism disorder (1); head and neck squamous cell carcinoma (1); hyperglycaemia (1); influenza (1); lipid metabolism disorders (1); liver disease (1); lung carcinoma (1); lymph node metastasis (1); lymphoma (1); metabolic disorders (1); myeloid malignancies (1); nasopharyngeal carcinoma (1); neurological disorders (1); pancreatic adenocarcinoma (1); Pancreatic cysts (1).
A further 10 diseases each share a sentence with CEL in 1 paper.